CD44 (CD44 molecule (IN blood group))
Diseases named in the same sentence as CD44 in open-access papers (continued):
Sharing a sentence is not in itself a finding about the gene and the disease.
tumor (continued). "Here, we have discussed liposome-based nanocarriers targeting CD44 tumor cells by using the most potent ligand hyaluronic acid (HA) to bind with target CD44 cells." (PMID 35431911, 2021). "The cell proliferation inhibition efficacy of targeted DOX-NPs exhibited a strong dose-dependent pattern, with the maximum inhibition of tumor cell proliferation found at a higher concentration of DOX in CD-44-expressed cell lines." (PMID 33530291, 2021). "CD44 has attracted unusual attention from scientist since it was shown that particular CD44v isoform appear in cancer cells during tumor progression." (PMID 34257584, 2021). "Detecting CD44 in serum was proposed as a simple, non-invasive way to study tumor burden and metastasis in gastric and colon cancer." (PMID 34599251, 2021). "Despite the success of these approaches, along with mediated tumour growth inhibition in several CD44+ carcinoma cells and xenograft mice, they have yet to be translated into clinical application in human trials." (PMID 34944493, 2021). "The ratio of CD44+ CD90+ CD133+ cells in tumor tissues was notably higher, compared with that in normal tissues." (PMID 34746322, 2021). "Thanks to its surface plasmon resonance property, GNR/HA-DC exhibited noticeable photothermal conversion capacity, which was beneficial for realizing cancer-specific mild-temperature PTT especially for CD44-overexpressed tumor cells." (PMID 34041494, 2021). "With the employment of the Clinical Proteomic Tumor Analysis Consortium (CPTAC), the protein level of MMP9 and Vimentin were positively associated with CD44 in ccRCC tissues." (PMID 34934046, 2021). "Hyaluronic acid prevents leakage of siRNA or pDNA during delivery and specifically targets tumor cells with overexpressed CD44 membrane receptors." (PMID 34306980, 2021). "It has been reported that CD44v6-CAR T cells eradicated the CD44+ tumor cells efficiently along and produced the anti-tumor cytokines." (PMID 34412685, 2021). "The QCM-D, with the Au electrode coated with poly-L-lysine, was used for the capture of CD44 overexpressed tumor cells." (PMID 35056189, 2021). "Successful use of its clinical potential, particularly for therapeutic targeting, will likely require a greater mechanistic understanding for the biological and molecular contexts of the tumor–supporting vs. tumor–suppressing properties of CD44." (PMID 34827550, 2021). "According to the CGGA database, the expression levels of FANCD2 and CD44 were positively correlated with the grade of the tumor." (PMID 34689169, 2021). "Others have also reported that CD44 interaction with HA induced malignant behavior of the tumor cells, which resulted in the initiation of several pathways, such as src/MAPK, PI3/Akt, and translocation of Snail/β-catenin to the nucleus." (PMID 33540535, 2021). "The specific binding of HA to CD44 can make HA-based nanodrug delivery system localize and concentrate on tumor sites." (PMID 33792436, 2021). "CD44 was also found to be related to angiogenesis, tumor aggressiveness, and worse prognosis in HNSCC." (PMID 34359786, 2021). "Prostaglandins are major lipid mediator in CSCs and celecoxib treatment of ApcMin/þ mice reduced number of CD133+CD44+ cells and tumor burden." (PMID 34804950, 2021). "This further confirms the successful uptake of the nanocomplex mediated by the CD44 tumor homing effect with successful endosomal and lysosomal escape." (PMID 35431911, 2021). "The expression of XBP1s, CXCR4, and CD44 in tumor biopsy samples was downregulated in siRNA lentivirus-transfected xenografts." (PMID 34093792, 2021). "CD44 is a single-pass type I transmembrane protein that has shown to be closely related to tumor development." (PMID 34249910, 2021). "As expected, we isolated ALDH+CD44+CXCR4+CD24+ cells from the tumour derived from the PDX model by cell sorting." (PMID 34247196, 2021). "CD44 is a well-known cancer stem cell marker and plays a role in tumor metastasis in different cancer types." (PMID 34439211, 2021).
tumor (continued). "Hyaluronan, a non-sulfated glycosaminoglycan in the ECM, is also a common target, due to the CD-44-hyaluronan interaction’s influence on tumor progression." (PMID 33572559, 2021). "When 89Zr-anti-CD44 was injected into HT29 tumor-bearing Balb/c nude mice with a total Ab dose of 300 μg, PET/CT images at day 4 demonstrated clearly visible HT29 tumors and showed splenic uptake that appeared lower than previous observed with low Ab dose." (PMID 33594192, 2021). "The majority of control tumor cells appear mesenchymal with pervasive expression of CD44 and VIM and an astrocytic subpopulation expressing GFAP at high levels." (PMID 33975634, 2021). "We found that the CD44+CD133+ fraction of Caco-2 cells is substantially enriched in tumor-initiating-like cells, which can be defined by functional analysis." (PMID 33994850, 2021). "Mesenchymal-like bCSCs, characterized as CD24−/CD44+, are primarily quiescent and are localized at the tumor invasive front, whereas epithelial-like bCSCs express aldehyde dehydrogenase (ALDH) proliferatively and are located more centrally." (PMID 33802575, 2021). "In an in vivo model, CD24−/low/CD44+ cell-injected mice showed enhanced tumor progression and lung metastasis via upregulation of tumor progression-related molecules and altered host immune responses." (PMID 34502547, 2021). "CD44 is a major hyaluronan receptor shown to play a crucial role in the activation of tumor-promoting signaling pathways." (PMID 34573355, 2021). "The SDDS is composed of two components: 1) intravenous injection of tumor CD44-targeted thermosensitive liposomes (TSL) preloaded with BML and Ptx, and 2) MW-induced hyperthermia to simultaneously achieve drug release and tumor ablation." (PMID 34867360, 2021). "It has been shown that CD44 can mediate the stemness of tumor cells and participate in metastasis by binding to hyaluronic acid." (PMID 38650282, 2021). "Hyaluronic acid (HA) is a popular molecule for tailoring nanocarriers to target CD44, a transmembrane glycoprotein overexpressed in cancers, with implications in tumor cell proliferation, differentiation, motility, and chemoresistance." (PMID 34066710, 2021). "As previously reported, the expression of CD44 was demonstrated to efficiently indicate tumor burden and metastatic potential in gastric patients." (PMID 34758833, 2021). "Since CD44+ receptors are commonly overexpressed in tumour cells, HA becomes a necessary and powerful targeting component in a drug delivery nanocomposite." (PMID 35011272, 2021). "The expression of CD44 in patients with pancreatic neuroendocrine tumours was positively related to poor tumour differentiation, high histological grade and an advanced stage." (PMID 34944493, 2021). "CD44 is a member of the cell adhesion molecules that have been proposed as having conflicting functions, i.e., either being tumor-promoting or tumor-suppressing in BC." (PMID 34685653, 2021). "Together with other cell surface molecules, CD44 was proposed as a marker of cancer stem cells in HCCs, which are responsible for tumor progression and aggressiveness." (PMID 34065048, 2021). "LbL nanoparticles that show improved cell internalization due to selective interaction with CD44 cell surface receptors as well as tumor-responsive pH-induced cell drug delivery were developed by Dreaden and co-workers." (PMID 33981532, 2021). "The level of CD44 can regulate the sensitivity of tumor cells to ferroptosis and the stability of SLC7A11, a key component of the cystine-glutamate antiporter related to ferroptosis regulation." (PMID 34249910, 2021). "The overexpression of distinct CD44 isoforms (CD44v) standard (CD44s) depends on the tumour type and stage." (PMID 34513617, 2021). "In BC, the CD44+/CD24- subpopulation isolated from tumor xenografts displayed high expression levels of HH signaling molecules compared to more differentiated cell subsets." (PMID 34354950, 2021).
tumor (continued). "The major cell-surface receptor for HA is CD44; its expression is increased in the sites of tumor invasion and one of its isoforms, CD-44v3, has been closely linked to progression and to chemoresistance of UADT SCC." (PMID 34199373, 2021). "Besides the EPR effect-based tumor targeting and CD44-driven tumor targeting HA could also work in a tumor microenvironment to trigger the reprogramming of tumor-associated macrophages towards anti-tumor M1 type macrophages." (PMID 33671291, 2021). "Targeting of the hyaluronic acid-CD44 glycocalyx complex results in significant reduction in the extravasation of tumor cells." (PMID 33637851, 2021). "In vitro inhibition of VEGF by either siRNA or Bev activated the expression of CD44 in cultured GSCs and significantly promoted invasion and migration of the tumor cells." (PMID 33543833, 2021). "Then, we compared the CD44 expression level among different cell types and found that only malignant tumor cells, TAMs, and T cells express CD44." (PMID 35187044, 2021). "After doxycycline treatment, surgical tumor samples showed a significant decrease in the expression level of the stemness markers CD44 and ALDH1 respect to matched pre-operative and pre-doxycycline samples." (PMID 34381714, 2021). "More importantly, HA, as a specific ligand for CD44 often overexpressed on tumor cells, was also applied for the tumor-targeted delivery of anticancer drugs and imaging contrast media." (PMID 34885645, 2021). "We immunohistochemically stained our TMA with three proteins integral to the Reg4 pathway: Reg4, CD44, and CD44ICD and looked into associations with clinical parameters of tumor aggression." (PMID 33659040, 2021). "Transplantation of GDC40(GFP)CD44 into the brains of NOD‐SCID mice generated a much more diffusely extended tumor mass with an indistinct tumor margin compared with that of GDC40(GFP), which showed a relatively demarcated margin." (PMID 33543833, 2021). "CSCs are identified based on their functional activity (self-renewal and serial tumor progression) and phenotypic markers (CD44+/CD24− signature and aldehyde dehydrogenase-1 (ALDH) activity)." (PMID 34502547, 2021). "Pancreatic cancer stem cells (PCSCs) promote tumor growth and progression through several mechanisms, including tumor-initiation by inducing stem cell markers CD44, CD24, and CD133, and evasion of conventional therapies." (PMID 34820419, 2021). "Taken together, these results demonstrate that the CD44-positive tumours suggest a poorer prognosis." (PMID 34944493, 2021). "The positive expression of CD44 in tumor tissues of pre-treatment SCLC patients is correlated with poor PFS." (PMID 34187156, 2021). "The frequency of BCSCs (Lin-CD44+CD24- cells) in tumor samples was expressed as a percentage of total tumor cells by flow cytometry." (PMID 34778599, 2021). "The tissues from area-A (stroma alone) and area-B (tumor/stroma junction) were dissected from the PDX tumor-bearing mice, and the tissue sections were stained with antibodies specific to CD44 (labeled with FITC) and HA (tagged with rhodamine)." (PMID 34770956, 2021). "IHC staining CD44 protein in Panc-1 tumor tissues treated with Fraction B showed that the percentage of CD44 expression in Panc-1 tumor tissues was notably reduced by 71.4% compared to that of control tissues (p = 0.0009)." (PMID 34349642, 2021). "In malignant pleural mesothelioma, HA and CD44 have been shown to ease cell motility, invasion and consequently, tumour progression." (PMID 34944493, 2021). "IHC-stained sections of the same 12 LA tissue samples demonstrated consistent membranous staining of the CSC marker CD44 in tumor cells, as well as membranous and cytoplasmic staining in stromal cells." (PMID 34685477, 2021). "The combination of sorafenib and 3-HAA significantly reduced the proportion of CD133+CD44+ tumor cells than either sorafenib or 3-HAA alone." (PMID 34230478, 2021).
tumor (continued). "Whereas, TCGA mesenchymal subtype GBM is characterized as immunosuppressive and therapy resistant tumor, the significance of CD44 expression preference in specific GBM molecular subtype and tumor cell cellular state is unclear." (PMID 35187044, 2021). "The TMA was immunohistochemically stained for Reg4, CD44, and CD44ICD proteins and analyzed to identify associations with tumor characteristics, recurrence and overall survival." (PMID 33659040, 2021). "CD44 is cancer stem cell marker and critical player in regulating self-renewal, tumor initiation, metastasis, and chemoradio-resistance." (PMID 34408983, 2021). "After tumor sphere-forming in CD44+/CD133+ pancreatic cells, high levels of Notch/Bcl-2 and loss of miR-34 have been identified." (PMID 34094034, 2021). "The generator of key pro-tumorigenic PGE2, PTGES is significantly upregulated in ALDH+ cells and conversely downregulated in CD44+/CD24- sorted tumor cells." (PMID 35127497, 2021). "Further, tumor-specific memory T cells (TMEs) were analyzed by detecting the ratio of CD8+CD44+ T cells." (PMID 34362890, 2021). "Our recent work demonstrated that circulating tumor cell (CTC) clusters and polyclonal metastasis of TNBC are driven by aggregation of CD44+ cancer stem cells (CSC) and associated with an unfavorable prognosis, such as low overall survival." (PMID 33995681, 2021). "CD44 members contain CD44s (standard CD44) and CD44 v1-v10, and they both have unique cell adhesion properties that could cause the interaction between two different cell types or one cell type and its surrounding matrix, sequentially accelerating the aggregation and migration of tumor cells." (PMID 33531990, 2021). "SSZ, a well-characterized specific inhibitor of xCT-mediated cystine transport, suppresses CD44-driven tumor growth and activates p38 mitogen-activated protein kinase signaling." (PMID 33401672, 2021). "Cancer cells also recruit macrophages to the tumor by secreting exosomes containing IL-8, VEGF, HGF, and CD44 mRNA that re-educate nearby monocytes, which differentiate into TAMs once they enter the tumor stroma." (PMID 34621752, 2021). "The therapeutic benefit of the prepared targeted delivery system was based on binding of the HA ligand on to the CD44 overexpressed receptor on the tumor cells." (PMID 35431911, 2021). "RT-qPCR assays showed that the transition from MCF10A to the more aggressive downstream tumor cell populations resulted in only minor increases in the global expression of CD44." (PMID 34086943, 2021). "Their internalization into tumor cells via HA-receptor CD44-mediated endocytosis proved the efficiency of this supramolecular association for imaging of biomarker." (PMID 35479531, 2021). "The HA-coated micelle targeted CD44 on tumor cells and increased OVA cellular uptake more than 10 times." (PMID 33800172, 2021). "Cldn7 knockdown enhanced proliferation, migration, and sphere formation but inhibited apoptosis in HCT116CD133+CD44+ cells in vitro and promoted tumour formation in vivo." (PMID 34281572, 2021). "Remarkably, SOX21-AS1 knockdown was shown to reduce proliferation, invasion, tumor growth, stem factor expression of the CD44+/CD24− population in vitro and in vivo." (PMID 33802575, 2021). "The lymph nodes and primary tumor of BC0145 PDX were harvested for staining with anti-CD44 and anti-TMCC3 antibodies." (PMID 33742122, 2021). "Regression analysis identified CD44 marker as an independent predictor for tumor staging and grading (p < 0.0001) of CRC patients." (PMID 34837915, 2021). "CD44 is an overexpressed receptor on the surface of cancer cells, and it plays several roles in tumor progression." (PMID 34834387, 2021). "Surface modification of the GNO-based nanocomposites with polysaccharides like chitosan (CH) and hyaluronic acid (HA) greatly improves its biocompatibility, while targeting the payload to the CD44 positive tumor cells (GNO@CH-HA)." (PMID 34138386, 2021).
tumor (continued). "Significant suppression of overall tumor growth and CD44+/CD24−, MDR1+3–5 and PD-L1+6,58 cell types that are involved in stemness and invasion was observed indicating the significance of SF in effectively controlling TNBC growth." (PMID 34873206, 2021). "HA acts as a ligand for CD44 protein, which can target tumor cells overexpressing CD44 receptor, thus enabling targeted drug delivery." (PMID 33792436, 2021). "To address this possibility, we isolated MC38 tumor-infiltrating CD8+CD44+PD1+ T cells for transcriptomic analysis by RNA-seq." (PMID 34819502, 2021). "HA binding to CD44 is known to induce the expression and activity of MMPs, involved in degradation of extracellular matrix components and tumor progression." (PMID 33958632, 2021). "Several receptors such as integrin, folate receptors (FR), transferrin, EGFR, sigma, GPCR, and CD44 are overexpressed in tumor cells." (PMID 35431911, 2021). "In the early stage selection, highly malignant tumor cells with CD44 expression were determined by HA, which appears in the normal stroma in the early stage invasion." (PMID 34770956, 2021). "The tumour volume formed by HCT116CD133+CD44+shCldn7 cells was also larger than that formed by control cells (P < 0.05)." (PMID 34281572, 2021). "In SW480 and DLD-1 cells, the combination of niclosamide and metformin yielded a significant decrease of tumor spheres and a lower proportion of CD44+/CD166+ cells compared to those of cells treated with niclosamide or metformin alone." (PMID 34298652, 2021). "Multiple genes, such as FBP1, PLOD2, VCAN, and CD44 have been demonstrated to participate in epithelial-mesenchymal transition (EMT) promotion of tumor metastasis." (PMID 33836688, 2021). "The tumor stroma was also examined by the expression status of cancer stem cell markers, CD44 and ESA." (PMID 33836674, 2021). "Analysis of the TCGA-GBM dataset showed significant upregulation of CD133 and CD44 stem cell surface markers in GBM tumour tissue compared to non-tumour tissue, in agreement with previous studies." (PMID 34066147, 2021). "It has also been shown that a higher CD44 expression in GBM patients correlates with worse patient prognosis due to increased tumour cell proliferation, invasion and resistance to radio- and chemotherapy." (PMID 34066147, 2021). "Mechanistically, miR-34a suppressed PCSC properties (e.g., prostasphere establishment, migration and invasiveness of CD44+ cells, and serial tumor transplantation) by directly targeting CD44." (PMID 33763422, 2021). "While the relationship between CD133 expression and colorectal tumor volume or stage varies among studies, a meta-analysis of 27 tumorgenicity studies found a twofold increase in tumor volume in cells that expressed CD133 or CD44." (PMID 34290978, 2021). "Compared with the xenograft model of CD44-negative cells, there were more micrometastases in the alveoli in the xenograft model of CD44-positive cells (i.e., mesenchymal tumor stem-like cells)." (PMID 34563053, 2021). "GSI, a γ-secretase inhibitor IX, was reported to be capable of inhibiting the proliferation, migration, invasion, and tumor sphere formation of CD44 (+) GCSCs by inhibiting the Notch signaling pathway." (PMID 35047411, 2021). "Using the mIHC platform, the adhesion molecule CD44—a transmembrane glycoprotein receptor known to promote tumour cell plasticity—and VM were induced around the mosaic VM-forming cells." (PMID 34638234, 2021). "Enhanced cleavage of CD44 was shown to facilitate tumor cell motility, which has been observed in many human tumors, including breast, colon, gastric, ovarian, lung, and others." (PMID 33540535, 2021). "CD44 is a multifunctional transmembrane glycoprotein participating in cell–cell and cell–matrix interactions during tumorigenesis, angiogenesis, tumor growth, and metastasis." (PMID 34400947, 2021). "In OSCC, cells derived from both tumors and tumor margins expressed CD44, had the ability to form spheroids and displayed chemoresistance." (PMID 33303029, 2020).